ITGA5 (integrin subunit alpha 5)
Diseases named in the same sentence as ITGA5 in open-access papers (continued):
Sharing a sentence is not in itself a finding about the gene and the disease.
tumor (continued). "This study demonstrated that ITGA5-EVs-148a inhibited CAF-mediated paracrine effect on tumor cell migration." (PMID 39099892, 2024). "In particular, ligand-receptor pair analysis revealed that the SPP1 signal was mainly involved in the interaction among tumor-associated macrophage (TAM), T cells, and malignant cells via SPP1–CD44 and SPP1–(ITGA5 + ITGB1) ligand-receptor pairs." (PMID 38282028, 2024). "A comparison of gene expression in normal ovaries and tumor tissue revealed decreased mRNA levels of ITGA5 and VIM in OC patients." (PMID 38786089, 2024). "Similar to uptake study, the transcytosis ability was significantly inhibited by depletion of serum or ITGA5‐specific antibody, suggesting that FN/ITGA5 interaction also contributed significantly to the effective tumor transcytosis." (PMID 38482976, 2024). "The tumor volume of ITGA5-EVs and EVs-148a group was significantly suppressed compared with control." (PMID 39099892, 2024). "The analysis of scRNA-seq data showed that SPP1 was highly expressed in malignant cells and HPC-like cells and mainly involved in the interaction among tumor-associated macrophage, T cells, and malignant cells via SPP1–CD44 and SPP1–(ITGA5 + ITGB1)." (PMID 38282028, 2024). "The nanocarrier is capable of recruiting fibronectin (FN) enriched protein corona, resulting in effective tumor targeting and penetration through FN/ITGA5 mediated transcytosis." (PMID 38482976, 2024). "Meanwhile, the tumor fluorescence signal in the ITGA5-EV group was higher than that in the EV group." (PMID 39099892, 2024). "In vivo imaging and ex vivo fluorescence imaging indicated that ITGA5-EVs exhibited enhanced targeting and accumulation at the tumor site." (PMID 39099892, 2024). "Nutrient depletion within tumor tissues is considered to promote the subnuclear accumulation and endocytosis of ligand-engaged ITGA5/ITGB1 via inhibition of mTORC1." (PMID 38892190, 2024). "Other studies have shown that ITGA5 is an early prognostic factor for NSCLC, and the high expression of ITGA5 indicates poor prognosis and a higher risk of tumor metastasis." (PMID 39275122, 2024). "SPP1 was mainly involved in the interaction among tumor-associated macrophages, T cells, and malignant cells via SPP1–CD44 and SPP1–(ITGA5 + ITGB1) ligand-receptor pairs." (PMID 38282028, 2024). "We acknowledge that ITGA5 on tumor endothelial cells shall likely contribute to the tumor targeting of PAZA NPs, which will be further studied in the near future." (PMID 38482976, 2024). "ITGA5 stimulated tumor progression via up regulating EFNB2 in laryngeal squamous cell carcinoma (LSCC)." (PMID 38741195, 2024). "COL5A2, HMGCS2 and ITGA5 expressed in the tumour compartment and cytoplasmatic as well as WNT9Bnuc in the stroma were favourable prognostic factors for OS (p < 0.05) in univariate analysis." (PMID 38361045, 2024). "In vivo experiments demonstrated that ITGA5-EVs-148a significantly suppressed the tumor growth and the expression levels of ITGA5, PCNA, ACTA2, and FSP." (PMID 39099892, 2024). "Microscopic analysis further demonstrated that the tumor accumulation of ITGA5-EVs was higher than that of EVs." (PMID 39099892, 2024). "ITGA5 and SLC7A1 were found to be overexpressed in CC tumor tissues and were associated with a worse prognosis, except for LCK, GCH1 and TNFRSF9." (PMID 38903179, 2024). "In gastrointestinal tumors, ITGA5 promoted tumor progression through the activation of the FAK/AKT pathway and was correlated with tumor purity and levels of immune infiltration." (PMID 36999964, 2023). "Functionally, ITGA5 has been reported to promote tumor progression, metastasis, and drug resistance." (PMID 36999964, 2023). "To test the function of ITGA5 in angiogenesis, we treated HUVECs with conditional medium (CM) from tumor cells transfected with siNC or siITGA5 and performed tube formation assays and 3D spheroid sprouting assays in vitro." (PMID 36999964, 2023).
tumor (continued). "ITGA5 is not only expressed in tumor cells, but it has also been reported to be expressed in CAFs, TAMs and chimeric antigen-receptor expressing T cells." (PMID 37284199, 2023). "Together, these data indicated that macrophage-induced tumor cell ITGA5 expression can promote enzalutamide resistance of bone-metastatic PC." (PMID 36749798, 2023). "In this study, ITGA5 expression was also increased in tumor tissues of HNSCC patients, which had a relation with low overall survival." (PMID 36742137, 2023). "The contents of Ki-67 and ITGA5 in tumor tissues were downregulated in mice transfected with shRNA-ACTN1." (PMID 36742137, 2023). "Among them, CDKN2A (also known as P16 gene), FN1, and ITGA5 were identified as tumor markers which predict poor prognosis." (PMID 38248716, 2023). "In tumor cells with ITGA5 knockdown, qRT‐PCR and Western Blotting revealed decreased expression of ANGPT1, ANGPT2, and VEGFA, when compared to control cells." (PMID 36999964, 2023). "All these results consistently suggest that ITGA5, EFNB2 or p-S6 in tumor tissues have good sensitivity and specificity as diagnostic markers for LSCC." (PMID 36438491, 2022). "In our study, the knockdown of JAK2 and ITGA5, including fibronectin (upstream factors involved in the initial tumor spheroid formation) mediated significant reductions in the levels of LMO2 and LDB1." (PMID 36359204, 2022). "Similar to the CDX models, the growth of tumor size and weight in ITGA5 siRNAs group was remarkably retarded compared with that in the siNC group." (PMID 36438491, 2022). "The tumor-bearing mice were treated with intratumoral injection of either ITGA5 siRNA or siNC, together with intraperitoneal injection of CDDP or normal saline (NS) for three weeks." (PMID 36438491, 2022). "Alternatively, genetic depletion of L1CAM, serpin B1, ARP2/-3, RUNX1, or ITGA5 in tumor cells has been demonstrated to attenuate vessel co-option." (PMID 35951441, 2022). "Consistent with the in vitro results, EFNB2 re-expression abrogated the suppressive effects of ITGA5 depletion on xenograft growth, tumor cell proliferation (as assessed by Ki-67 index), and tumor angiogenesis (as assessed by CD31 index)." (PMID 36438491, 2022). "Using co-culture systems and miRNA microarrays, we found the tumor-suppressor function of HSCs-derived exosomal miR-148a-3p in HCC through ITGA5/PI3K/Akt axis and highlighted the importance of TME in HCC development." (PMID 35414782, 2022). "In summary, ITGA5, as a crucial downstream effector of mTORC1, promotes cell proliferation, metastasis, angiogenesis, and tumor growth of LSCC." (PMID 36438491, 2022). "Based on the TCGA and the GTEx, we firstly examined the ITGA5 transcriptional abundance in 33 tumor types." (PMID 35371978, 2022). "TGF-β, in turn, further activates fibroblasts to provide tumor prosurvival signals, including elevated expression of ITGA5, while promoting ECM production and upregulation of EGF to maintain persistence of the signaling loop." (PMID 35267539, 2022). "We also investigated the expression of ITGA5 in patients with HCC using TCGA database and found that ITGA5 was significantly upregulated in tumor tissues, which associated with poor OS in HCC patients." (PMID 35414782, 2022). "In contrast, the tumor sizes and weights of the ITGA5 OE group were obviously greater than those in the vector control group." (PMID 36438491, 2022). "More importantly, knockdown of ITGA5 suppressed LSCC tumor growth and sensitized LSCC to CDDP therapy in our CDX and PDX models." (PMID 36438491, 2022). "ITGA5 protein expression in the tumor tissues of animals in the NC group and ITGA5 overexpression group was detected by immunohistochemistry, and the results showed that ITGA5 was significantly increased in the tumor tissues of the ITGA5 overexpression group." (PMID 36193075, 2022).
tumor (continued). "Crosstalk between OVCA cells and CAFshighα5, moreover, leads to secretion of EGF, which initiates a bidirectional paracrine loop and subsequent increase in tumor cell ITGA5, further stabilizing tumor–stroma interactions." (PMID 35267539, 2022). "Depletion of ITGA5 attenuated cell proliferation, migration, angiogenesis, tumor growth, and tumor metastasis, whereas overexpression of ITGA5 exerted the opposite effect." (PMID 36438491, 2022). "Previous studies mainly focused on the role of ITGA5 in tumor cells, but recent studies found that ITGA5 is also expressed in cancer-associated fibroblasts, TAMs and chimeric antigen receptor expressing T cells." (PMID 33711961, 2021). "Its differential expression was correlated with the organ specificity of tumor metastasis, thus ITGA5 was recognized as a potential biomarker for cancer treatment." (PMID 34573489, 2021). "It is possible that ITGA5 inhibits differentiation of tumor stem cells but promotes tumor proliferation and invasion, of which the specific mechanism is worthy of further study." (PMID 33828988, 2021). "ITGA5 forms a receptor for extracellular fibronectin, which known to be involved in the formation of malignant tumor cells and tumor vascular systems." (PMID 34660316, 2021). "We showed that the silencing or pharmacological inhibition of ITGA5 markedly reduced tumor outgrowth in experimental models of bone metastasis or tumorigenesis." (PMID 33420367, 2021). "More importantly, the correlation between ITGA5 and tumor-infiltrating immune cells and markers in different tumor microenvironments was also analyzed." (PMID 33711961, 2021). "Here, we found that abrogating ITGA5 in human MDA-MB-231 cells also blunted tumor burden in the bone marrow, whereas the formation of pulmonary micrometastases remained unaffected." (PMID 33420367, 2021). "Experimentally, ITGA5 silencing impaired tumor cell adhesion to fibronectin, migration, and survival." (PMID 33420367, 2021). "ITGA5 silencing also reduced tumor cell colonization of the bone marrow and formation of osteolytic lesions in vivo." (PMID 33420367, 2021). "And the positive correlation between ITGA5, NOD2, P2RX4, RIPK2, SLC7A1 and immune score indicated that the tumor tissue in the high-risk group is highly infiltrated by immune cells, which is consistent with risk score." (PMID 33828988, 2021). "Pharmacological inhibition of ITGA5 with humanized monoclonal antibody M200 (volociximab) recapitulated inhibitory effects of ITGA5 silencing on tumor cell functions in vitro and tumor cell colonization of the bone marrow in vivo." (PMID 33420367, 2021). "Integrin family including ITGA5, expressed by tumor and tumor-related host cells, mediates a variety of cellular effects, leading to tumor progression and metastasis." (PMID 33828988, 2021). "FN1, ITGA5, THBS2, and LAMA1 were associated with cell adhesion and metastasis, and the expression of TGFB1, COL4A1, COL4A2, and THBS2 inhibited tumor growth." (PMID 34370778, 2021). "ITGA5 was related with tumor purity, B cell, Macrophage cell, Neutrophil cell, and Dendritic cell invasion in SKCM TIME." (PMID 34660316, 2021). "Results revealed significant differences in ITGA5 expression levels when comparing normal and tumor tissues." (PMID 33711961, 2021). "A significant correlation was observed between high ITGA5 mRNA expression levels and high tumor cell invasiveness (p = 0.0083)." (PMID 33420367, 2021). "Previous studies have shown that ITGA5 is overexpressed in various cancer types, where it is involved in tumor progression." (PMID 34263426, 2021). "The expression level of ITGA5 was detected by Oncomine and Tumor Immune Estimation Resource (TIMER)." (PMID 33711961, 2021). "The silencing of ITGA5 led to a 60% reduction of tumor cell adhesion to fibronectin, whereas tumor cell adhesion to glass, poly-D-Lysine, and laminin remained unchanged." (PMID 33420367, 2021).
tumor (continued). "Recent studies revealed that ITGA5 plays a crucial role in different tumor cell subgroups and cell-cell interactions." (PMID 33711961, 2021). "To further select the key genes in the complex network, we analyzed all of genes integrating with the clinical categories and found that TGFβ2, GNG11, PDGFB, and ITGA5 were changed among different patients’ tumor stages, states, T categories, and grades." (PMID 33115518, 2020). "There was one overlapping gene (ITGA5) when we compared the post-GWAS genes and dysregulated genes in primary tumours vs. adjacent normal tissue resulting from the three studies, of Taylor, Grasso and Yu." (PMID 32397189, 2020). "The secretion of crucial chemokines in the serum was significantly reduced in tumor-bearing Itga5-floxed animals." (PMID 32082485, 2020). "Patient age, tumor grade, status of IDH mutation and expression of seven genes (SEMA3A, SEMA3D, SEMA3F, SEMA3G, ITGB3, ITGA5, and VEGFA) significantly correlated with patient OS (p < 0.05)." (PMID 33036421, 2020). "This consequently promotes ITGA5 (integrin α5) expression in tumor cells, which in turn further enhances the tumor-stromal interaction inside the heterotypic spheroids." (PMID 32546182, 2020). "Higher levels of CYP2E1 have been linked with the production of procarcinogenics, while upregulation of ITGA5 is known to be involved in higher invasiveness of tumor cells." (PMID 32078659, 2020). "In the context of OC tumor tissues, ITGA5 staining was predominantly detected at the invasive front of HGSOC specimens and areas adjacent to stromal CAFs." (PMID 30710055, 2019). "Mechanistically, we demonstrated that tumor cells promote EGF secretion by CAFs within the MU microenvironment that consequently drives ITGA5 expression in ATCs, which in turn further strengthens the tumor–stromal interaction inside MUs." (PMID 30710055, 2019). "Up-regulation of ITGA5 in tumor cells after coculture with CAFs in heterospheroids was thus attenuated in the presence of imatinib." (PMID 30710055, 2019). "Three single guide RNAs (sgRNAs) were designed, and ablation of ITGA5 was most evident in tumor cells edited with sgRNA2, confirmed with T7 endonuclease I (T7E1) assay and immunoblotting." (PMID 30710055, 2019). "CircRNA_100085, AK02180, IFNG, ITGA5, and DES were significantly associated with tumor size and TNM." (PMID 30446877, 2019). "The deletion of the rs55958994-associated enhancer leads to the down-regulation of ITGA5, CDH23, and CNTN1, to defects of tumor initiation, growth, and invasive migration, and to a decrease in the percentage of CSCs." (PMID 31328168, 2019). "The integrin subunit alpha 5 (ITGA5) is regulated by transforming growth factor β, and is involved in the adhesion of tumor cells to laminin in human OS cells." (PMID 30153287, 2018). "We found limited genetic concordance between primary and secondary tumor sites with private mutations in FLT4, MTOR, ITGA5, SETD2, PBRM1, and BRCA1 on progression." (PMID 29088767, 2017). "ITGA5 is a member of the integrin family mediating cell-to-cell adhesion and can drive migration in tumor cells." (PMID 25537511, 2015). "Base on the blood Gluc assay, we dynamically and accurately evaluated the sensitivity of anoikis in tumor cells with the different levels of ITGA5." (PMID 25537511, 2015). "Our results provide the first evidence that, in aggressive HCCs, miR-26a governs tumor cell anoikis sensitivity, at least in part, by downregulating the expression level of ITGA5." (PMID 25537511, 2015). "Collectively, these findings demonstrated that Akt inactivation is an essential downstream signaling pathway during ITGA5 suppression-induced tumor cell anoikis." (PMID 25537511, 2015). "Several common target genes in the networks were down-regulated in both wt and mt tumor cells, such as ITGA5 and S100A2 (adhesion and migration), SERPINE1 (angiogenesis), CDKN1A (growth arrest), and PLAU and SERPINE5 (proteolysis)." (PMID 24069219, 2013).
tumor (continued). "Overexpression of ITGA5 leads to increased cellular adhesion and interaction with fibronectin, resulting in promoted tumor metastasis." (PMID 21838876, 2011). "The functional relationship between Src inhibition and regulation of the receptor tyrosine kinase platelet-derived growth factor receptor beta (Pdgfrb) as well as the fibronectin receptor integrin alpha 5 (Itga5) has been commonly observed in tumour cells." (PMID 21152443, 2010). "In addition, some genes including ABCG1, KRAS, MMP2, MMP9 were inhibited by cyAV3.3 in homospheroids, which indicates the direct effect of ITGA5 inhibition on resistance in tumor cells." (PMID 41584360, 2026). "This indicates that ITGA5 may promote the survival of tumor cells by activating the PI3K signaling pathway." (PMID 41602372, 2026). "This investigation systematically examines the pathophysiological contributions of migrasome-associated fibroblast subpopulations to metastatic dissemination in pancreatic malignancies, with particular emphasis on TSPAN4/ITGA5 expression gradients across tumor ecosystem compartments." (PMID 40443671, 2025). "3.Triptolide effectively targets ITGA5, suppressing tumor progression in OC." (PMID 40770810, 2025). "Analysis of tumor clones revealed SCC‐specific COL6A1+/ITGA5+ carcinoma cells which produce CXCL16." (PMID 40776410, 2025). "However, the ITGA5 KO tumor sphere nearly abolished this effect, even when fibronectin was reintroduced, further confirming a critical interplay between fibronectin and ITGA5 in mediating efficient tumor penetration of PAZA." (PMID 38482976, 2024). "In contrast, ITGB3 and ITGA5 — which have been associated to high tumor stages in patients — are not upregulated upon liver metastasis formation in vivo." (PMID 38775153, 2024). "To examine whether any RGD motif recognition integrins in LN229TAZ(4SA) cells could be involved, we knocked down ITGB1 or ITGA5 individually in the tumor cells through shRNAs targeting each of them (Fig. EV2D,E)." (PMID 38806658, 2024). "ITGA5-EVs exhibited enhanced targeting ability and accumulation at the tumor site." (PMID 39099892, 2024). "Integrin alpha 5 (ITGA5) is a member of the integrin family of adhesion molecules that play critical roles in cell adhesion and signal transduction and are closely associated with tumor invasion, progression, and chemoresistance." (PMID 38887185, 2024). "Moreover, a previous study reported that miR-26a governs tumor cell anoikis sensitivity by downregulating ITGA5 expression in HCC." (PMID 39288140, 2024). "ITGA5 knockdown inhibited tumor growth while promoting CDDP sensitivity in LSCC cells." (PMID 38741195, 2024). "Thus, the simultaneous increase in CHRNA7, CERK and ITGA5 expression upon the SLURP-1 treatment illustrates the activation of pro-oncogenic intracellular signaling pathways in the tumor." (PMID 37854069, 2023). "Moreover, tumor cells transfected with ITGA5‐targeting siRNA decreased ability to promote endothelial tube formation in vitro." (PMID 36999964, 2023). "ITGa5 forms a complex with ITGβ1 and is responsible for tumour cell migration and invasion." (PMID 37174646, 2023). "In addition, the expression of miR-148/152 family members was negatively correlated with that of ITGA5 in tumor tissues." (PMID 36765401, 2023). "Hence, we selected FAP and ITGA5 as biomarkers to detect CAFs and pan-CK as a marker of tumor cells in the following experiment." (PMID 36831470, 2023). "Furthermore, there is mounting evidence that Integrin A5 (ITGA5), which plays a major role in the adhesion, migration, and invasion of cancer cells, is highly expressed in several malignancies and contributes to tumor progression." (PMID 37822877, 2023). "CAFs could recruit ITGA5high ascitic tumor cells to form metastatic units, which further sustain ascitic OC cells’ ITGA5 expression by EGF secretion." (PMID 37383389, 2023).